MDM2 (MDM2 proto-oncogene)
Diseases named in the same sentence as MDM2 in open-access papers (continued):
Sharing a sentence is not in itself a finding about the gene and the disease.
cancer (continued). "Another MDM2 inhibitor APG-115 synergized with PD1 inhibitors in a mouse model of cancer immunotherapy by promoting M1 macrophage polarization and T cell activation." (PMID 38577591, 2024). "Oncogenic MDM2, commonly over-expressed in various human cancers, can potentially enhance carcinogenesis and resistance to apoptosis." (PMID 39144622, 2024). "MDM2 (Murine double minute 2) is widely known for its significant contributions to cancer development, including promoting sustained angiogenesis, metabolic reprogramming, growth stimulation, apoptosis evasion, metastasis, and immunosuppression." (PMID 38893137, 2024). "Consistently, cancer cell lines that overexpress MDM2 show attenuated levels of γH2AX induced by TOP2 poisons." (PMID 38263255, 2024). "One advantage of nutlins is their specificity for MDM2, which allows for selective targeting of cancer cells that overexpress MDM2 while sparing normal cells." (PMID 37297833, 2023). "Nutlins are a class of small-molecule inhibitors of MDM2 that have shown promise in preclinical studies for cancer therapy." (PMID 37297833, 2023). "Our findings also suggest that ACP52C‐resistant cancer cells express higher levels of MDM2 p60 by the CASP2‐mediated cleavage of MDM2 p90." (PMID 37845006, 2023). "High Nrf2 activity in cancer cells leads to the upregulation of various proteins associated with cancer progression, including ABCG2, VEGF, HO-1, Bcl-2, p62, and MDM2." (PMID 37759607, 2023). "The prevalence of MDM2 amplification has been reported, in various types of cancer, from 3.5% to 5.5%, mostly in sarcomas." (PMID 38002335, 2023).
cancer (continued). "Although MDM2 promotes cancer growth through its stimulation of angiogenesis, metastasis, and metabolic reprogramming, its anti-apoptotic roles are important for the development of therapeutic solutions." (PMID 37314603, 2023). "In this cancer model, further evidence suggests that MDM2 also regulates angiogenesis by increasing the expression levels of transcription factors such as HIF-1α and vascular endothelial growth factor (VEGF), thereby promoting tissue neovascularization." (PMID 37509256, 2023). "While the identified antimetabolites are used as chemotherapeutics for a variety of cancers, clinical trials with MDM2 inhibitors have had only a limited success." (PMID 36727434, 2023). "Significantly, along with the expanding use of genomic profiling for customized cancer treatment, MDM2 continues to function as a potentially effective molecular therapeutic target." (PMID 37081989, 2023). "Recently, several MDM2 inhibitors have even been discovered, which are currently under investigation in clinical studies for their possible capacity to treat cancer, e.g., glioblastoma." (PMID 38002335, 2023). "Since its identification, various cancer-promoting roles of MDM2 such as growth stimulation, sustained angiogenesis, metabolic reprogramming, apoptosis evasion, metastasis, and immunosuppression have been established." (PMID 37314603, 2023). "This shows that the regulation of MDM2 is different between various cancer cell types and the effect of IU1 can vary." (PMID 37711852, 2023).
cancer (continued). "In most cancer cell types the response to MDM2 inhibition is a reversible form of cell cycle arrest of little therapeutic value, with only few cell lines undergoing apoptosis." (PMID 36681780, 2023). "A limited number of Phase 3 clinical trials with MDM2 inhibitors have been performed for cancers outside the CNS." (PMID 37509518, 2023). "A study on invasive ductal breast carcinoma revealed the role of MDM2 in facilitating the invasion of malignant tumors by mediating the expression of matrix metalloproteinases (MMPs)." (PMID 37314603, 2023). "Recently, cancer research protocols have introduced clinical-stage spirooxindole-based MDM2 inhibitors." (PMID 37156796, 2023). "The MDM2 gene is involved in different parts of the cancer signaling cascade, being a direct target of regulation by MIR605." (PMID 36901860, 2023). "Dysregulation of MDM2 can therefore result in increased cell proliferation, decreased apoptosis, and ultimately, cancer development." (PMID 37297833, 2023). "The murine double minute 2 (MDM2) gene (also referred to as human double minute 2 (HDM2)) is well recognized for its growth-promoting role in various cancers." (PMID 37314603, 2023). "MDM2 has recently gained attention as an effective therapeutic target due to its clear correlation to cell cycle control and cancer." (PMID 37049742, 2023). "We discovered that MDM2, PTGS2, EGFR, and VEGFA are the key genes regulated by JCF and closely associated with the development of cancer." (PMID 37361218, 2023). "Although further studies are required, it is warranted to investigate the anti-cancer value of drugs targeting MDM2 and/or HIF-1α in RB or even other solid tumor types." (PMID 36741966, 2023). "Several MDM2 inhibitors have been developed and are currently being explored for their possible use in cancer treatment." (PMID 37509518, 2023).
cancer (continued). "Owing to its diverse functioning and huge significance in anti-apoptosis, various anti-cancer therapies targeting MDM2 have been developed." (PMID 37314603, 2023). "MDM2 overexpression is a common characteristic in various types of cancer, allowing cancer cells to evade normal cell division control and promote uncontrolled growth and metastasis." (PMID 37764441, 2023). "Taking together, the pivotal role of MDM2 in cancer development is of great significance for the development of therapeutic solutions." (PMID 37314603, 2023). "In recent years, numerous highly selective and potent small-molecule MDM2 inhibitors have been discovered, with nine of them undergoing clinical trials for cancer treatment." (PMID 37764441, 2023).
cancer (continued). "For GP5, CDK12 inactivation and gains of AKT1, GSK3B, PIK3CA, CCND1, and MDM2 were identified as the top truncal druggable targets that would be most likely to obtain a durable response due to their presence in all cancer cells." (PMID 37828555, 2023). "MI-219 also revealed potent inhibitory properties against MDM2 protein with apoptosis induction in cancer cells and safe behavior towards normal cells." (PMID 36677676, 2023). "First, the Oncomine, GENT2, and GEPIA2 databases were used to evaluate the patterns of the differentially expressed MDM2 gene in distinct cancer types." (PMID 37049742, 2023). "To begin, we queried this database for changes in MDM2 expression using 5408 samples from 5208 LGG cancer patients across 9 studies." (PMID 37049742, 2023). "Mdm-2 inhibitors unsuccessfully struggle to be approved as an anti-cancer therapy for almost two decades." (PMID 36913303, 2023). "MDM2 also contributes to the development of vascularization to support the growing nutritional demands of cancers." (PMID 37314603, 2023). "Using the Western blot analysis, we found that the up-regulation of the MDM2 protein was an early response to the CAP treatment in the cancer and normal cells." (PMID 38002354, 2023). "Currently, 28 clinical trials are evaluating the possible therapeutic use of MDM2 inhibitors in cancer." (PMID 37509518, 2023).